IL6 (interleukin 6)
Diseases named in the same sentence as IL6 in open-access papers (continued):
Sharing a sentence is not in itself a finding about the gene and the disease.
tumor (continued). "Mechanistically, afatinib and dacomitinib induce STAT3 activation via promoting autocrine IL6 secretion in cancer cells, which potentiates drug resistance via a paracrine loop between fibroblasts and tumor cells." (PMID 34944848, 2021). "Consistently, IL6 promoted tumor sphere formation and enhanced both mRNA and protein expression in stem cell genes." (PMID 33576874, 2021). "Most antitumor therapies can induce inflammation by killing tumor cells and normal tissues, and in this process, the expression levels of multiple inflammatory cytokines, including IL-6, IL-8, TNF-α, and other inflammatory factors, are upregulated." (PMID 34976809, 2021). "Mass cytometry (cytometry by time of flight, CyTOF) analysis of tumor-derived single-cell suspension showed that genetic ablation of IL-6 increased the population of cytotoxic CD8+ T cells in GBM." (PMID 34103524, 2021). "Tumor-derived IL-6 is capable of inducing programmed death-ligand 1 (PD-L1) expressing myeloid cells in vitro." (PMID 33466236, 2021). "Next, we explored the roles of BLT2 and 5-/12-LOX in transgenic mice with lung-specific expression of mutant KRAS (KrasG12D) and observed that BLT2 or 5-/12-LOX inhibition decreased IL-6 production and tumor formation." (PMID 34635780, 2021). "Upon stimulation by proinflammatory factors (LPS, TNF-α), TAMs activate into M1-like macrophages and kill tumor cells by producing reactive oxygen species and inflammatory cytokines (e.g. IL-6 and TNF-α)." (PMID 34178692, 2021). "Viral interleukin-6 promotes cell proliferation, tumor invasion, and angiogenesis by suppressing caveolin 1, which plays a role in tumor development mediated by DNA methyltransferase 1 (DNMT1)-targeted STAT3 acetylation." (PMID 35008848, 2021). "Studies have shown that there is active expression and increased secretion of IL-6 in or around tumor tissues." (PMID 33495421, 2021). "In contrast, in the syngeneic tumor cell engraftment system, elevated cytokine expression of IL-1β, IL-6, IL-2 and IFN-γ in GABARAP KO immune cells probably inhibited tumor cell growth." (PMID 34502326, 2021). "IL6/JAK/STAT3 signaling promotes tumor proliferation, invasiveness, and metastasis and suppresses antitumor immune response in the TME." (PMID 33790966, 2021). "We focused on IL-6, because IL-6 was upregulated by tumor CM treatment, and it is reportedly involved in drug resistance in tumor cells." (PMID 34226586, 2021). "DOX administration in tumor-bearing mice significantly ameliorated the tumor-induced upregulation of IL-1β, IL-6, TNF-α, and Mcp-1." (PMID 34445729, 2021). "In line with this, IL-6 has been detected to be abnormally elevated in the cerebrospinal fluid and within the tumor of GBM patients." (PMID 34376733, 2021). "Further, this action of IL-17 was thought to be mediated by inducing overexpression of IL-6 in the tumor cells, promoting infiltration of M2 TAMs into the tumor." (PMID 33996630, 2021). "IL-6 is produced by multiple cell types in the tumor microenvironment, including tumor-infiltrating immune cells, stromal cells and tumor cells." (PMID 33500736, 2021). "Treatment with anti-IL-6 or anti-IL-6 receptor antibodies reduces PD-L1 expression patient-derived xenografts, which indicates that tumor-induced peripheral immunosuppression promotes brain metastases." (PMID 33466236, 2021). "Specifically, we demonstrate that tumor-derived interleukin 6 (IL-6) expressed by high metastatic cells mediates a tumor–BM cross talk, which in turn leads to increased levels of MDPs." (PMID 34140316, 2021). "The pro-inflammatory cytokines IL-6, IL-8, and TNFα possess tumor-promoting functions and increased tissue levels are associated with many types of cancer." (PMID 35145494, 2021). "Some of our previous findings have shown impairment of the placenta due to the presence of cancer or some tumour factors, such as proinflammatory cytokines interleukin-6 (IL-6), interferon-gamma (IFN-γ), and tumour-necrosis factor (TNFα)." (PMID 33916290, 2021).
tumor (continued). "In cancer, tumor-derived expression of IL-1, IL-6 and TNFα have been shown to promote accumulation and immunosuppressive abilities of MDSC." (PMID 33805598, 2021). "The upregulation of gp130 on the tumor cell surface also leads to the response to a low concentration of IL-6 in low-grade inflammation." (PMID 33668122, 2021). "In agreement, inhibition of IL-6 with a neutralizing antibody reduced tumor cell growth in bone in this model." (PMID 33809315, 2021). "IL-6 is involved in boosting T cell trafficking to lymph nodes and to tumour sites, where they have the opportunity to become activated and execute their cytotoxic effector functions, respectively." (PMID 33923108, 2021). "In the TME, tumor-associated macrophages (TAM) promote neovascularization, tumor growth, and metastasis through cytokines (i.e., IL-6, IL-8, and IL-10) that clearly overlap with the SASP." (PMID 34206425, 2021). "Further analyses revealed that blocking tumor EphA2 function reduced osteoclast precursor maturation into functional osteoclasts through an IL‐6–dependent mechanism in coculture." (PMID 33869989, 2021). "IL6 was significantly modulated in 70% of tumor types, revealing either up- or down-regulation in an approximately equal number of tumors." (PMID 34576335, 2021). "The suppression of exosomal miR101 stimulates the expression and secretion of IL1A and IL6 in macrophages and leads to inflammation in the tumor microenvironment." (PMID 34362882, 2021). "A recent study shows that the OvCa tumor stroma of metformin-treated patients exhibits lower IL6 expression via inhibition of NF-KB." (PMID 34440224, 2021). "They found that a subtype of CAFs with high expression of α-SMA and low expression of IL6 was activated only when tumor cells came into direct contact with PSCs, and they defined those CAFs as myCAFs." (PMID 34336821, 2021). "Interleukin-6 (IL-6) is generated and secreted by multifarious types of cells, including tumor cells." (PMID 33981768, 2021). "Novel strategies are now designed to target CAF-secreted tumor promoting or immunosuppressive molecules (IL-6, TGFb, etc....) or inhibiting subtype specific signaling that would ablate a particular CAF population." (PMID 34663337, 2021). "STAT3 hyperactivation in tumor cells were generally induced by elevated IL-6 in the tumor microenvironment in the majority of human cancers." (PMID 34922636, 2021). "In CRPC, the overexpression of cytokines such as IL-6 is known to promote tumor progression and drug resistance." (PMID 33810413, 2021). "The upregulated expression of VEGF, IL-8, and IL-6 was also observed in human melanoma tumor cell lines treated with norepinephrine." (PMID 34869378, 2021). "We investigated the role of IL-6 for tumor immunosuppression in GBM, initially using a genetic approach." (PMID 34103524, 2021). "Mast cells have been shown to promote dendritic cell migration to lymph nodes through TNF-α, histamine, and IL-6 and promote anti-tumor T-cell phenotypes through histamine." (PMID 34063789, 2021). "Myeloid inflammation is associated with high expression of IL-6, prostaglandins, and the CXCL8 family of chemokines, which suppress the anti-tumor immunity." (PMID 33968762, 2021). "Sunitinib, which delays tumor progression, is highly correlated with decreased circulating levels of the inflammatory molecule IL-6 and soluble c-KIT." (PMID 34948424, 2021). "In this process, tumor cell-derived Jagged1 simulates Notch signaling in osteoblasts, which increases the IL-6 release and OC differentiation." (PMID 34745140, 2021). "IL-6 is vitally important for many malignant cells; moreover, it is a critical molecule significantly shaping their tumor microenvironment landscape." (PMID 34681685, 2021). "Our data indicate that a substantial fraction of human PDAC tumors exhibit expression of IL-6 in malignant cells and further that IL-6 is produced by many established PDAC tumor cell lines." (PMID 33851955, 2021).
tumor (continued). "Examples of such tumour-promoting cytokines are IL-6, tumour necrosis factor α (TNF-α) and transforming growth factor β (TGF-β), where several clinical trials targeting these cancer-promoting cytokines are ongoing." (PMID 34830872, 2021). "IL-6, a cytokine in OvCa cells, initiates signaling pathways, leading to tumor proliferation, angiogenesis, and chemo-resistance." (PMID 34440224, 2021). "JAK/STAT3 signaling pathways play an important role in mediated IL-6 inhibition of tumor cell proliferation, invasion, and metastasis and antitumor immunity." (PMID 34745261, 2021). "IL-6 is a proinflammatory cytokine involved in the stimulation of angiogenesis of the tumor microenvironment, as well as in the enhancement of endothelial cell proliferation and migration." (PMID 34206393, 2021). "Our study reveals that EphA2 functions in tumors to promote osteolysis of the bone via osteoclast differentiation, at least in part through regulation of IL‐6 production in tumor cells." (PMID 33869989, 2021). "IL-6 had broad effects on leukocyte survival, proliferation, differentiation, and recruitment, and was able to promote anti-tumor immunity to attain tumor control." (PMID 33808494, 2021). "In the OvCa TME, cancer cells secrete IL6, which inhibits the maturation of DCs and induces immunosuppressive alternatively activated TAMs, which compromise the activation of tumor-infiltrating T cells." (PMID 34248988, 2021). "Upon its recruitment to BME, BM-MSCs differentiates into cancer-associated fibroblasts, resulting in a further increase in MCP-1, GRO-α, IL-6, and IL-8 levels in the tumor microenvironment." (PMID 34681692, 2021). "IL-6 via STAT-3 has been shown to promote tumor cell proliferation in many cancers, including oral squamous cell carcinoma via DNA hypomethylation, prostate cancer through androgen receptor activation, and colon cancer." (PMID 34307156, 2021). "This anti-tumor effect was mediated by recruitment of CD8 T cells and NK cells likely by CCL3 secretion, IL-6 secretion potentially leading to an anti-proliferative impact on tumor cells, and also reduced mature blood vessel density." (PMID 34063789, 2021). "Here, we found that IL6 expression in primary tumor tissues or bone marrow (BM) metastases was closely associated with the disease risk and prognosis of NB patients." (PMID 34790130, 2021). "Enhanced levels of IL-6 play a key role in STAT3 signaling in tumor formation and the development of CRC." (PMID 33996591, 2021). "The IL-6 pathway is essential for the transformation of fibroblasts into CAFs, which serve as fertile soil for tumor progression." (PMID 34588424, 2021). "Noteworthy, it has also been previously shown that senescence-associated secretory phenotype (SASP) triggers the expression of tumor-promoting cytokines, including interleukin-6 (IL-6), which is an autophagy-inducing signal in cancers." (PMID 33542201, 2021). "IF-IHC demonstrated that co-expression of intracellular Rab37 and IL-6 with tumor-infiltrating CD45+ immune cells (CD45+Rab37+IL-6+) was observed especially in late stage patients." (PMID 34093869, 2021). "For example, obesity induced IL-6 promote the polarization of Mφ into a tumor-promoting type and thus exacerbate CAC progression." (PMID 33390844, 2021). "The IL‐6 receptor inhibitor tocilizumab and IL‐6 antagonist siltuximab have been shown to augment the anti‐tumor activity of chemotherapeutic agents in preclinical trials, and further clinical studies are expected." (PMID 34977870, 2021). "A recent study exhibits that inhibition of SIRT1 by caveolin-1 in senescent fibroblasts promotes the secretion of interleukin 6 (IL-6) and stimulates tumor growth." (PMID 33390835, 2021). "This tumor growth delay was underpinned by elevated serum interleukin-6 (IL-6) levels, a lower percentage of central memory CD4+ T cells in the spleen, and a larger percentage of CD4+ T cells and effector memory CD8+ T cells in nonirradiated tumors." (PMID 36405502, 2021).
tumor (continued). "Dectin-1 derived from particulate β-glucan converted M2 bone marrow-derived macrophages into M1-like phenotype, which expresses proinflammatory cytokines such as TNF-α, iNOS, IL-1β, and IL-6 to inhibit the development of the tumor." (PMID 34094602, 2021). "ARG1 is induced in tumour-infiltrating myeloid cells such as TAMs, MDSCs, and DCs through the secretion of tumour-derived factors and metabolites, including IL-4, IL-13, IL-6, M-CSF, GM-CSF, TGF-β, and cAMP." (PMID 34685679, 2021). "The antitumour effects of both exosomes originating from tumours and heat-stressed tumour cells were found to be dependent upon IL-6." (PMID 34781996, 2021). "It was revealed that persistent increased IL-6 concentration, after tumor resection, has an unfavorable value in predicting the presence of distant metastases." (PMID 34441316, 2021). "Pro-inflammatory M1 TAMs promote phagocytosis of tumor cells and anti-inflammatory M2 TAMs secrete immunosuppressive cytokines (e.g., IL-10, IL-6, and TGFβ)." (PMID 34901012, 2021). "IL-6 has already been directly shown to be not only related to tumor progression and aggressiveness, but also found in GBM secretome." (PMID 33902430, 2021). "For example, a myokine, namely, interleukin (IL)-15 was reported to have an important role in T cell proliferation; exercise induces myokine IL-6, which releases and activates natural killer cells, thereby reducing tumor growth." (PMID 34551011, 2021). "IL-6 is a proinflammatory cytokine involved in tumor growth, invasion and metastasis, known to be elevated in CRC patients with a poor prognosis." (PMID 33619304, 2021). "In vitro studies on PC cell lines have shown that tumor cells with IL-6 increase androgen receptor (AR) expression and function on these cells, affecting many convenient cellular processes." (PMID 34868907, 2021). "Upregulation of IL-6 in tumor cells, induced by SDF-1α, is due to downstream activation of FAK-AKT and ERK1/2 signaling pathways, thereby supporting cell survival and chemoresistance." (PMID 33673405, 2021). "In conclusion, in a TME rich in eATP, P2X7R activation in PSCs promotes IL-6 release that through STAT3 activation in cancer cells would promote tumor progression." (PMID 34440697, 2021). "The activated Tregs are recruited into tumor by tumor-derived immunosuppressive cytokines IL-6 and CCL2 (P); for simplicity, we represent both cytokines by CCL2." (PMID 34061898, 2021). "Induced autophagy in CAFs can stimulate secretion of IL-6 and IL-8 followed by aggressive tumor development." (PMID 34575052, 2021). "Except IL-6, CAFs-derived Wnt2 can also increase tumor angiogenesis in CRC, owing largely to Wnt2-upreglated expression of some proangiogenic proteins." (PMID 34660589, 2021). "MDSCs require the activation of inflammatory cytokines, such as IL-6 and TNF-α, and tumour-associated cytokines, such as GM-CSF and M-CSF, to form a population of immunosuppressive cells." (PMID 34193120, 2021). "Linking tumor-NLRP3 induction of IL-6/STAT3 to immunosuppression, we assessed PMN-MDSCs in bone marrow and spleen from tumor-bearing mice treated with OLT1177." (PMID 34531850, 2021). "IL-6 affects many hallmarks of cancer, such as proliferation, cell growth, and inhibition of apoptosis, and can enable the tumour cells to become drug-resistant." (PMID 34359796, 2021). "The NF-κB signaling pathway, which is constitutively expressed in many different types of cancer and involved in tumor formation and progression, regulates the cytokines interleukin-6 (IL-6) and interleukin-8 (IL-8)." (PMID 33921329, 2021). "IL-6 can be produced at the tumor site by various cells, but it can also leak and be active in remote body parts." (PMID 34681685, 2021). "Restoring IL‐6 expression to control levels rescued osteoclast differentiation induced by 4T1.ΔC tumor cells, and a neutralizing anti‐human IL‐6 antibody significantly inhibited osteoclast differentiation induced by 4T1.V cells (p < 0.05)." (PMID 33869989, 2021).
tumor (continued). "Immunosuppressive factors in the tumor microenvironment, including IL-6, TGF-β, PGE2, and indoleamine 2,3-dioxygenase (IDO), can block NK cell activation." (PMID 33746989, 2021). "The pleiotropic proinflammatory cytokine IL-6 can independently predict tumor recurrence, poor survival, and tumor metastasis in HNSCC." (PMID 33804419, 2021). "IL6 and IL8 have been identified as direct CEBPB and CEBPD targets, and there is evidence that cancer-cell-derived IL-6 and IL-8 promote tumor growth and metastasis and therapeutic resistance." (PMID 34065488, 2021). "When anti-PD-L1 is combined with anti-IL-6, the response of tumor cells to the PD-L1 treatment can be improved." (PMID 34305902, 2021). "IL-6 is a pro-inflammatory cytokine released in the breast TME by both cancer cells and stromal cells such as fibroblasts, tumour associated macrophages, and helper T cells." (PMID 33758206, 2021). "Next, miRNA expression levels were determined to identify the factor in tumor CM or in EVs that induced IL-6 in HMVECs." (PMID 34226586, 2021). "Significant upregulation of Il-6 was observed in the skeletal muscle tissue of tumor-bearing mice, and the administration of LiCl completely inhibited the tumor-induced increase in Il-6 expression." (PMID 33925786, 2021). "MDSCs can inhibit the differentiation of tumor-specific CD4+ T cells into CD4+ Th1 cells through IL-6 production." (PMID 34681680, 2021). "Blood transfusions are associated with promoting a proangiogenic environment inducing tumor growth by releasing cytokines IL6, IL10, and TNFα, and regulatory T-cell activation suppressing the anti-tumoral Th1 response." (PMID 34202030, 2021). "A vast majority of these studies also propose IL-6 as a prognostic marker in HCC, and a high serum IL-6 level was correlated with tumor burden and aggressiveness." (PMID 35127527, 2021). "A variety of tumor cells also secrete IL-6, which can target macrophages to regulate the tumor microenvironment." (PMID 34863141, 2021). "As a result of the examination of the tumor microenvironment, decreased inflammatory cell (CD11b+ and F4/80+) uptake, decreased expression of cytokines (IL1α/β, IL6, CCL2, CXCL5, and TNFα) and pro-inflammatory enzymes (COX-2, and NOS2) were determined." (PMID 34073059, 2021). "The polarized TAMs then contribute to tumor progression, angiogenesis, and immunosuppression by expressing factors such as IL-6, VEGF, inducible nitric oxide synthase (iNOS), and arginase." (PMID 33917501, 2021). "Pro-inflammatory cytokines such as interleukin-1, interleukin-6, tumor necrosis factor α, are not only important impact factors for albumin production, but also critical in oncogenesis, angiogenesis and tumor progression." (PMID 33596518, 2021). "For example, hyperactivation of the IL6/JAK/STAT3 pathway promotes tumor metastasis and chemoresistance via induction of EMT through the upregulation of EMT-inducing transcription factors, such as Snail, Twist-1 and ZEB1." (PMID 34944855, 2021). "IL-6 is a major pro-inflammatory cytokine secreted in the tumor microenvironment from both tumor and stromal cells which influences almost all hallmarks of cancer to promote cancer growth and progression." (PMID 34445170, 2021). "Conversely, TAMs can secrete chemokines and cytokines, particularly IL-6, IL-8, and IL-10, that are involved in tumor growth, angiogenesis, tumor invasion, and the depression of immunity." (PMID 33916915, 2021). "IL-6 is one of the major cytokines released in the tumor microenvironment, and it is involved in multiple processes of tumor development, such as in modeling the immune responses in cancers." (PMID 34829995, 2021). "The lower levels of BIM and PTEN potentially contribute to the survival of IL6+/+;Eμ-myc tumor cells." (PMID 33651821, 2021). "Here, we found that the pro-inflammatory factors—IL-1β, IL-6, and IL-8—were significantly increased in fibroblasts treated with exosomes derived from tumor cells." (PMID 34261453, 2021).